FTH1 (ferritin heavy chain 1)
Diseases named in the same sentence as FTH1 in open-access papers (continued):
Sharing a sentence is not in itself a finding about the gene and the disease.
Sepsis (29 papers, 2018 to 2025). Sepsis is defined as life-threatening organ dysfunction caused by a dysregulated host response to infection. "Here, mice deficient in Fth1 in the myeloid lineage had longer survival, lower organ damage, and lower levels of inflammatory cytokines compared to normal, Fth1-expressing animals, when sepsis was induced." (PMID 35008695, 2021). "In macrophages, the most differentially expressed genes after sepsis include S100a9, S100a8, Hbb-bs, Fth1, AW112010, Spic, Cxcl2, Cd14, Hmox1, and Vcam1." (PMID 38343542, 2024). "However, there were also reports stating that the expression of FTH1 is up-regulated in lipopolysaccharides (LPS)-induced sepsis modeling rats." (PMID 38304189, 2024). "The results of our study show that ferroptosis was exacerbated in animal and cellular models of sepsis, as demonstrated by the decrease in the protein expression of Gpx4, increase in the protein expression of TF and FTH-1, and increase in serum Fe2+ levels compared with the sham groups." (PMID 37375325, 2023). "Elevated SLC39A8 expression enhances lipid peroxidation while downregulating GPX4, FTH1, indicating that SLC39A8-driven ferroptosis plays a crucial role in the depletion of monocytes during sepsis." (PMID 40959429, 2025). "Western blot analysis of ferroptosis-related proteins revealed that sepsis altered the expression of 4-HNE, FTH1, GPX4, ACSL4, PTGS2, and SLC7A11, which was reversed by ghrelin and Fer-1, indicating their role in inhibiting ferroptosis." (PMID 39857660, 2024). "Weis and colleagues showed, using different genetically modified mice lines with conditional deletion of the Fth1 gene, that FTH was necessary for disease tolerance in sepsis." (PMID 32325688, 2020). "In particular, our results are consistent with earlier reports showing that core genes involved in these pathways—such as FTH1 and GCLM, which are related to iron homeostasis and glutathione metabolism—were found to be upregulated in sepsis, promoting iron-dependent lipid peroxidation." (PMID 41346577, 2025). "Mir22hg silencing lightened ferroptosis and ferritinophagy in LPS-induced MLE-12 cells and sepsis mouse models, as presented by the downregulated MDA, ROS, Fe2+, NCOA4, and SLC3A2 levels, upregulated GPX4, GSH, and FTH1 levels, along with a decrease in autophagy." (PMID 38842666, 2024). "Although the free iron and MDA levels were significantly decreased in sepsis-induced ferroptosis in the present study, the expression level of FTH1 was lacked to be tested, which needed to be evaluated in our future study." (PMID 35038133, 2022). "Taken together, these experimental data suggested that YAP1 could suppress FTH1 autophagic degradation mediated by NCOA4, which was crucial for protecting pulmonary epithelial cells from sepsis-induced ferroptosis." (PMID 35979359, 2022). "The boxplot revealed 26 differentially expressed genes between the sepsis-induced ALI and control samples: Ncf2, Slc2a6, Cd44, Txnip, Slc2a1, Ubc, Hspb1, Zfp36, Arntl, Ddit4, Tnfaip3, Txnrd1, Mt1, Hmox1, Gch1, Gclc, Stat3, Egfr, Hif1a, Bach1, Socs1, Dusp1, Cdkn1a, Fth1, Steap3, and Alox12." (PMID 37081490, 2023). "Thus, the attenuating effect of RNH1 on LPS-induced relative FTH1 and HAMP mRNA expression and/or secretion may enhance rather than counteract sepsis." (PMID 38951571, 2024).
ovarian carcinoma (19 papers, 2015 to 2025). A malignant neoplasm originating from the surface ovarian epithelium. "The expression of IGF2BP1 and FTH1 was strongly linked to ovarian cancer grade malignancy." (PMID 37304234, 2023). "Lastly, most genes (FTL and FTH1) involved in the iron storage process displayed increased expression in ovarian cancer tissues, suggesting an association between this process and the initiation of ovarian cancer." (PMID 38186569, 2023). "LncRNA CACNA1G-AS1 can upregulate FTH1 to inhibit ferroptosis and promote malignant phenotypes in ovarian cancer cells." (PMID 40725394, 2025). "We also observed strict iron regulation in ovarian cancer through FTH1 and FTL, protecting cells from platinum- or high iron-induced DNA damage." (PMID 38740757, 2024). "To reveal how ovarian cancer regulates iron homeostasis, we found that iron can induce the expression of FTH1/FTL." (PMID 38740757, 2024). "Our results demonstrated higher levels of TRFC and FTH1/FTL proteins in ovarian cancer cells compared to immortalized ovarian epithelial cells." (PMID 38740757, 2024). "Our findings affirm the pro-cancer role of iron in ovarian cancer and reveal that iron advances platinum resistance by promoting DNA damage repair through FTH1/FTL/POLQ/RAD51 pathway." (PMID 38740757, 2024). "Bioinformatics analysis showed that FTH1 shared high sensitivity and accuracy in predicting the prognosis of ovarian cancer patients." (PMID 37304234, 2023). "Subsequent studies confirmed that FTH1 methylation was closely related to the prognosis of ovarian cancer patients." (PMID 37304234, 2023). "The results showed that in CACNA1G-AS1 knockdown ovarian cancer cells, FTH1 and IGF2BP1 expression significantly decreased, while IGF2BP1 overexpression reversed this change." (PMID 37304234, 2023). "All these results revealed that the FTH1 m6A methylation regulation pathway (CACNA1G-AS1/IGF2BP1) is closely related to ovarian cancer progression." (PMID 37304234, 2023). "Previous bioinformatics analysis showed that the expression levels of FTH1 methylation and m6A methylation regulators were obviously correlated with the prognosis of ovarian cancer patients." (PMID 37304234, 2023). "In contrast, in CACNA1G-AS1-overexpressing ovarian cancer cells, FTH1 and IGF2BP1 expression obviously increased, while IGF2BP1 downregulation reversed this change (consistent with IGF2BP1)." (PMID 37304234, 2023). "SKOV3 cells were transfected with plasmids containing RNA mimics and inhibitors (CACNA1G-AS1, IGF2BP1 and FTH1) to construct ovarian cancer cell models with different pathway expression states." (PMID 37304234, 2023). "All these results showed that the amount of CACNA1G-AS1 and FTH1 pulled down by the AGO2 antibody significantly increased in ovarian cancer cells transfected with IGF2BP1." (PMID 37304234, 2023). "The results confirmed that compared with ovarian cells and tissues, CACNA1G-AS1, IGF2BP1 and FTH1 expression levels were obviously increased in ovarian cancer samples." (PMID 37304234, 2023). "In this research, we constructed an FTH1 m6A methylation regulatory network in ovarian cancer through signal pathway detection in cell lines and clinical samples." (PMID 37304234, 2023). "Based on these results, in our study, we attempted to construct an FTH1 methylation regulatory network and explore its mechanism of action in ferroptosis and the malignant phenotypes of ovarian cancer at the molecular level by experimental analysis." (PMID 37304234, 2023). "Ferroptosis vulnerability is induced through autophagic degradation of ferritin (i.e., ferritinophagy) of ferritin heavy chain 1 (FTH1) in cisplatin-resistant ovarian cancer." (PMID 37842240, 2023). "Colony formation assays confirmed that the number of newly generated cells in the CACNA1G-AS1 overexpression group obviously increased, while this number correspondingly decreased after IGF2BP1 and FTH1 inhibition in ovarian cancer cells (p < 0.01)." (PMID 37304234, 2023).
ovarian carcinoma (continued). "Through pathway expression verification, we confirmed that the FTH1 m6A methylation regulatory pathway (CACNA1G-AS1/IGF2BP1) was obviously increased in ovarian cancer samples, and its expression was closely related to tumor malignancy." (PMID 37304234, 2023). "EdU assays showed that the proportion of new cells in the CACNA1G-AS1 overexpression group obviously increased (p < 0.01), while this proportion correspondingly decreased after IGF2BP1 and FTH1 inhibition in ovarian cancer cells (p < 0.01)." (PMID 37304234, 2023). "This suggests that platinum-induced DNA damage in ovarian cancer cells may trigger changes in cellular iron balance, potentially indicating an increased demand for iron and subsequent upregulation of FTH1 and FTL." (PMID 38740757, 2024). "However, little is known about the role of FTH1 m6A methylation in ovarian cancer (OC) and its possible action mechanisms." (PMID 37304234, 2023). "Ferritinophagy and ferroptosis-related indicator detection showed that CACNA1G-AS1/IGF2BP1-mediated FTH1 m6A methylation could inhibit ferritinophagy and ferroptosis in ovarian cancer cells." (PMID 37304234, 2023). "Cell function experiments confirmed that CACNA1G-AS1 could inhibit mitophagy and promote malignant phenotypes in ovarian cancer cells through IGF2BP1-mediated FTH1 m6A methylation." (PMID 37304234, 2023). "According to these results, we concluded that CACNA1G-AS1 could upregulate FTH1 via IGF2BP1-mediated m6A methylation in ovarian cancer cells." (PMID 37304234, 2023). "According to these results, we concluded that CACNA1G-AS1 could inhibit ferritinophagy via IGF2BP1-mediated FTH1 methylation in ovarian cancer cells." (PMID 37304234, 2023). "However, until now, there has been no relevant research exploring the upstream methylation regulatory network of FTH1 and its regulatory mechanism on ferroptosis and malignant phenotypes in ovarian cancer." (PMID 37304234, 2023). "This research confirmed that CACNA1G-AS1 is obviously upregulated in ovarian cancer samples and could upregulate FTH1 through IGF2BP1-mediated m6A methylation." (PMID 37304234, 2023). "Furthermore, IGF2BP1 can promote ferroptosis resistance by stabilizing ferritin heavy chain 1 (FTH1), signal transducer and activator of transcription 3 (STAT3), and parkinsonism-associated deglycase (PARK7) mRNAs in HCC, bladder cancer, ovarian cancer, and GC, respectively." (PMID 40584294, 2025). "Previous study revealed that ferritin heavy chain-1 (FTH1) could regulate ferritinophagy and affect intracellular Fe2+ content in various tumors, while its N6-methyladenosine (m6A) RNA methylation was closely related the prognosis of ovarian cancer patients." (PMID 37304234, 2023). "Therefore, we speculated that FTH1 could regulate ferroptosis through the ferritinophagy axis, thus affecting the malignant phenotype of ovarian cancer." (PMID 37304234, 2023). "Some scholars have constructed a prognostic grading model of ovarian cancer containing 5 ferroptosis-related factors (ALOX12, ACACA, SLC7A11, FTH1, and CD44) through biological analysis, which showed great value in the prognostic analysis of this disease." (PMID 37304234, 2023). "In colocalization analysis, we noticed that CACNA1G-AS1, FTH1 (green) and IGF2BP1 (red) colocalized in the cytoplasm of ovarian cancer cells." (PMID 37304234, 2023). "We constructed ovarian cancer cell models with different expression levels of CACNA1G-AS1 and IGF2BP1 and then performed WB to detect FTH1 and IGF2BP1 expression." (PMID 37304234, 2023). "Similarly, compared with normal tissues, CD44 and FTH1 expression were significantly downregulated in advanced-stage (FIGO III/IV) and high-grade (G3) ovarian cancer tissues." (PMID 41210681, 2025). "The results confirmed that in CACNA1G-AS1-overexpressing ovarian cancer cells, the red fluorescence intensity obviously increased, while these changes could be reversed through IGF2BP1 and FTH1 inhibition." (PMID 37304234, 2023).
ovarian carcinoma (continued). "First, we detected the colocalization of ferritin and lysosome labels, and the results confirmed that the colocalization of ferritin (FTH1) and lysosome (LAMP2) significantly increased in CACNA1G-AS1 knockdown ovarian cancer cells, while IGF2BP1 upregulation reversed this change." (PMID 37304234, 2023). "Scratch tests showed that the proportion of transversally migrated cells in CACNA1G-AS1-overexpressing ovarian cancer cells obviously increased (p < 0.01), while the proportion of migrated cells correspondingly decreased after IGF2BP1 and FTH1 inhibition (p < 0.01)." (PMID 37304234, 2023). "The methylation region and expression of FTH1 in ovarian cancer samples have not been clarified, and we plan to address this point by methylation sequencing and detection in the future." (PMID 37304234, 2023). "In CACNA1G-AS1 knockdown ovarian cancer cells, the ROS contents significantly increased, and these changes could be reversed by IGF2BP1 and FTH1 overexpression." (PMID 37304234, 2023). "ROS and Fe2+ detection showed that in CACNA1G-AS1-overexpressing ovarian cancer cells, the ROS and Fe2+ contents significantly decreased, while these changes could be reversed by IGF2BP1 and FTH1 inhibition." (PMID 37304234, 2023). "In contrast, in CACNA1G-AS1 knockdown ovarian cancer cells, the ROS and Fe2+ contents significantly increased, while these changes could be reversed by IGF2BP1 and FTH1 upregulation." (PMID 37304234, 2023). "In vitro cell experiments showed that LncRNA CACNA1G-AS1 could up-regulate FTH1 expression through IGF2BP1 axis, thus inhibited ferroptosis by regulating ferritinophagy, and finally promoted proliferation and migration in ovarian cancer cells." (PMID 37304234, 2023). "Moreover, in CACNA1G-AS1 knockdown ovarian cancer cells, red fluorescence intensity was obviously reduced, while these changes could be rescued through IGF2BP1 and FTH1 overexpression." (PMID 37304234, 2023). "In our research, the regulatory mechanism of IGF2BP1-mediated FTH1 methylation in this process and the relationship between ferroptosis and mitophagy in ovarian cancer cells were not fully elucidated, and these topics need to be further explored with subsequent experiments." (PMID 37304234, 2023). "The observation of mitochondrial morphology revealed that in CACNA1G-AS1 knockdown ovarian cancer cells, the mitochondrial volume was obviously reduced, the mitochondrial membrane was ruptured and the cristae vanished, while these changes could be rescued by IGF2BP1 and FTH1 overexpression." (PMID 37304234, 2023). "Overall, our results indicate that ovarian cancer cell growth in non-adherent culture conditions requires a modification of iron metabolism essentially aimed at preventing the accumulation of free and redox-active iron through the upregulation of its storage protein FtH1." (PMID 38033861, 2023).
Parkinson disease (16 papers, 2022 to 2026). A progressive degenerative disorder of the central nervous system characterized by loss of dopamine producing neurons in the substantia nigra and the presence of Lewy bodies in the substantia nigra and locus coeruleus. "The accumulation of iron in the brain, as observed in neurodegenerative diseases such as Parkinson’s and Alzheimer’s, has been linked to dysfunction in FTH1." (PMID 39941157, 2025). "KEGG pathway analysis revealed that FTH1 deficiency led to the promotion of N-Glycan biosynthesis, Parkinson's disease, and Huntington's disease, while inhibiting selenocompound metabolism and glycosaminoglycan biosynthesis." (PMID 38609896, 2024). "Interesting, downregulation of FTH1 has also been reported as a key mediator of ferroptosis and oxidative stress in other neurodegenerative diseases, such as Parkinson’s (PD) and Alzheimer’s disease (AD)." (PMID 40643497, 2025). "Increased survival of DA ergic neurons and reversal of ROS, GPX4, and FTH1 levels in SNpc after moxibustion application in a Parkinson’s disease (PD) model and improvement of motor deficits in it." (PMID 38846099, 2024). "For instance, downregulation of ferritinophagy by ferritin heavy chain 1 (FTH-1) overexpression suppressed cell death induced by ferroptosis in the model of Parkinson’s disease." (PMID 37522124, 2023). "In a study with in vivo and in vitro models of Parkinson’s disease, it was seen that miR-335 promotes ferroptosis by targeting ferritin heavy chain 1 (FTH1)." (PMID 37240889, 2023). "On the other hand, FTH1 is a part of the ferritin complex and can inhibit ferroptosis in Parkinson’s disease by ferritinophagy." (PMID 37858064, 2023). "In both animal models of Parkinson’s disease and brain tissues of patients, elevated expression of ferroptosis markers such as ferritin heavy chain 1 (FTH1) has been found, suggesting that ferroptosis plays an essential role in the pathogenesis of Parkinson’s disease." (PMID 39220446, 2024). "miR-335 mimic could decrease expression of FTH1, increase ferroptosis and facilitate progression of Parkinson’s disease." (PMID 36876051, 2023). "FTH1 was significantly downregulated in a rat model of Parkinson’s disease compared with controls." (PMID 36297287, 2022). "FTH1 silencing in 6-OHDA-induced cells has increased the pro-ferroptosis impact of miR-335 and promoted pathologic events in the course of Parkinson’s disease." (PMID 36876051, 2023).
bladder cancer (14 papers, 2021 to 2025). "Baicalin's anticancer effects are mediated by ferritin heavy chain 1, potentially leading to bladder cancer treatment by causing FTH1‐dependent ferroptosis." (PMID 40916076, 2025). "FTH1, responsible for encoding ferritin heavy subunits, emerged as a pivotal mediator of ferroptosis in bladder cancer cells induced by baicalin." (PMID 38317842, 2024). "TMBIM6, ferroptosis-related proteins (GPX4, SLC7A11, and FTH1), and calmodulin (CaM) expressions in bladder cancer and paracancerous tissues were obtained by immunohistochemistry." (PMID 40610429, 2025). "For example, baicalin induces ferroptosis in tumor cells by inhibiting FTH1, and FTH1 overexpression attenuates baicalin’s anticancer effects in bladder cancer." (PMID 40883748, 2025). "In this study, we observed elevated expression levels of TMBIM6 and ferroptosis-related proteins (GPX4, SLC7A11, and FTH1) in bladder cancer tissues, while CAM expression was significantly downregulated." (PMID 40610429, 2025). "Overexpression of FTH1 negated baicalin's anticancer benefits, suggesting a potential bladder cancer therapy." (PMID 40916076, 2025). "In the context of bladder cancer specifically, baicalin and Fin56 have been shown to induce ferroptosis through distinct molecular mechanisms, targeting FTH1 and GPX4, respectively." (PMID 40610429, 2025). "In bladder cancer and oral squamous cell carcinoma, baicalin targets the key protein of ferroptosis, ferritin heavy chain 1 (FTH1), inhibits its expression and induces ferroptosis." (PMID 39584140, 2024). "However, a controversial result revealed that baicalein-mediated ferroptosis of bladder cancer cells was triggered by downregulating FTH1, accompanied by the accumulation of ROS and iron." (PMID 39021832, 2024). "Baicalin exerts an anti-bladder cancer function by inhibiting FTH1 to induce ferroptosis." (PMID 38383815, 2024). "The down-regulation of FTH1 promotes ferroptosis in bladder cancer cells." (PMID 39330572, 2024). "Building upon these previous findings, our study has made a novel observation in bladder cancer: we identified significantly elevated expression levels of TMBIM6 and ferroptosis-related proteins (GPX4, SLC7A11, and FTH1) in clinical bladder cancer specimens." (PMID 40610429, 2025). "In bladder cancer cells, erianin evoked ferroptosis by inducing NRF2 inactivation characterized by decreased FTH1, GPX4, HO-1, and xCT/SLC7A11 expression as well as the accumulation of ROS and the depletion of GSH." (PMID 39021832, 2024).